RN7SL629P (RNA, 7SL, cytoplasmic 629, pseudogene)
Gene: Miscellaneous RNA gene on chromosome 5 (87,294,189 to 87,294,473, reverse strand). Ensembl gene ENSG00000241243.
Homologues: Orthologues: chimpanzee Metazoa_SRP (99% identical), pig Metazoa_SRP (65% identical). Paralogues in human: RN7SL1 (78% identical), RN7SL3 (78% identical), RN7SL2 (77% identical), RN7SL664P (77% identical), RN7SL126P (75% identical), RN7SL679P (75% identical), RN7SL296P (75% identical), RN7SL660P (75% identical), RN7SL230P (75% identical), RN7SL322P (75% identical), RN7SL357P (75% identical), RN7SL448P (75% identical), and 699 more.